FOXO1 (forkhead box O1)
Diseases named in the same sentence as FOXO1 in open-access papers (continued):
Sharing a sentence is not in itself a finding about the gene and the disease.
inflammatory bowel disease (4 papers, 2020 to 2025). A spectrum of small and large bowel inflammatory diseases of unknown etiology. "The immunoregulation and mechanism of FoxO1 in inflammatory bowel disease is the future research content of our group, which is also necessary to further explain the role of FoxO1." (PMID 32057181, 2020). "Therefore, genetic ablation of FoxO1 in T cells exacerbates the severity of inflammatory bowel disease (IBD) along with enhanced T cell activation and effector T cell (Teff) differentiation in mice." (PMID 35993049, 2022). "It means that increasing the levels of miR-425 (a type of small RNA molecule) in inflammatory bowel disease (IBD) can lead to the production of harmful Th17 cells by reducing the activity of a protein called Foxo1." (PMID 40417179, 2025). "In Inflammatory bowel disease (IBD), miR-425 play a role in the development of Th17 cells by targeting Foxo1." (PMID 40417179, 2025).
lung adenocarcinoma (4 papers, 2022 to 2025). A carcinoma that arises from the lung and is characterized by the presence of malignant glandular epithelial cells. "Trifluoperazine, in particular, enhances FOXO1 nuclear retention and reverses resistance mechanisms in lung adenocarcinoma by activating the KLF6/FOXO1 pathway." (PMID 40718442, 2025). "In our investigation into the impact of CGN and FOXO1 knockdown on cell metabolism in lung adenocarcinoma, we utilized CGN and FOXO1 siRNA for the knockdown and subsequently analyzed the cell metabolism parameters." (PMID 38338691, 2024). "In this study, we investigated the role and regulation of TJ protein CGN and transcription factor FOXO1 in the malignancy of human lung adenocarcinoma compared to normal lung epithelial cells." (PMID 38338691, 2024). "Trifluoperazine, a phenothiazine derivative, enhances FOXO1 nuclear retention and counters AKT-driven resistance to erlotinib by activating the KLF6/FOXO1 signaling pathway in lung adenocarcinoma." (PMID 40718442, 2025). "The results showed that the mRNA expression levels of ESR1, DDX3X, MAPK10, KIT, FOXO1, and MCL1 were significantly lower in both lung adenocarcinoma (LUAD) and lung squamous cell carcinoma (LUSC) tissues (p < 0.001) than normal lung tissues." (PMID 38180107, 2023). "Both HDAC inhibitors, TSA and Quisinostat, may have potential for use in therapy for lung adenocarcinoma via changes in the expression of CGN and FOXO1." (PMID 38338691, 2024). "In the present study, to investigate the effects of CGN and FOXO1 on the malignancy of NSCLC, we used A549 cells as human lung adenocarcinoma and primary human lung epithelial (HLE) cells as normal lung tissues and performed the knockdown of CGN and FOXO1 by siRNAs." (PMID 38338691, 2024). "In this present study, our findings indicate that the downregulation of CGN and FOXO1 leads to malignant cell proliferation, cell migration, and altered cell metabolism by upregulating CLDN-2 or CLDN-4 through the MAPK/AMPK pathways in human lung adenocarcinoma A549 cells." (PMID 38338691, 2024). "Thus, TSA and Quisinostat may have potential for use in therapy for lung adenocarcinoma via changes in the expression of CGN and FOXO1." (PMID 38338691, 2024). "In conclusion, in human lung adenocarcinoma, the downregulation of CGN induces malignancy via the upregulation of MEK-dependent CLDN-2 and cell metabolism and cell migration, and the downregulation of FOXO1 induces malignancy via the downregulation of CGN and CLDN-4 and cell proliferation." (PMID 38338691, 2024).
lymph node metastasis (4 papers, 2017 to 2025). "The mean mRNA level of either HBP1 or FOXO1 in non-invasive and invasive oral tumors (lymph node metastasis) was significantly lower than those of control normal tissues." (PMID 28099936, 2017). "Moreover, despite the lack of correlation between FOXO1 and miR-96-5p expression levels, miR-96-5p was related to lymph node metastasis." (PMID 41436994, 2025).
multiple myeloma (4 papers, 2019 to 2025). "Another example of FoxO1's tumor‐suppressive role is observed in multiple myeloma (MM), a plasma cell malignancy." (PMID 39533662, 2025). "Previous research by several scholars has analyzed 16 survival-associated autophagy genes (ARGs), including EVA1A, FOXO1, and HIF1, to assess the risk and adverse prognosis of multiple myeloma (MM)." (PMID 38529374, 2024). "Furthermore, blocking CD28 inhibited chemotherapy-induced cell apoptosis, and the CD28 signaling pathway was associated with the downstream activation of PI3K/Akt and inactivation of the FoxO1 in multiple myeloma." (PMID 31565151, 2019).
multiple sclerosis (4 papers, 2020 to 2021). A progressive autoimmune disorder affecting the central nervous system resulting in demyelination. "PD-1highIFN-γ+AREGhighFOXP3+ cells we describe here resemble the dysfunctional Th1 Tregs, which also display constitutive activation of PI3K/AKT/Foxo1/3 signaling cascade in multiple sclerosis patients." (PMID 34446704, 2021). "Interestingly, a recent study demonstrated that TIGIT signaling enhances the function of FOXP3+ Tregs from patients with multiple sclerosis by upregulating Foxo1 that blocks T-bet expression and limits IFN-γ secretion." (PMID 34314385, 2021).
Nephropathy (4 papers, 2016 to 2025). A nonspecific term referring to disease or damage of the kidneys. "Three genes (Frem2, Foxo1 and Setd7) have been implicated in nephropathy." (PMID 27736906, 2016). "Of these, Frem1, Foxo1, and Setd7 have been implicated in the pathogenesis of nephropathy." (PMID 27736906, 2016). "Reduced Klotho exacerbates tacrolimus-induced nephropathy through PI3K/AKT/FOXO1 signaling, where AKT-mediated FOXO1 phosphorylation modulates apoptosis via downstream effectors (e.g., Bcl-2/Bax)." (PMID 41488110, 2025).
oral squamous cell carcinoma (4 papers, 2018 to 2021). "For example, FoxO1 facilitated transcription of GAS5 to promote propofol‐induced oral squamous cell carcinoma apoptosis." (PMID 34346162, 2021). "Notably, propofol inhibited cell proliferation and promoted apoptosis in a dose‐ and time‐dependent manner by upregulating Forkhead Box O1 (FoxO1) expression in oral squamous cell carcinoma." (PMID 32596964, 2020).
ovarian tumors (4 papers, 2016 to 2025). "Developing 2 Uni-Vect systems to combine a constitutive HER2-targeting CAR with NFAT-inducible FOXO1 or TCF7, researchers validated improved proliferation and persistence of CAR-T cells in ovarian tumors." (PMID 40693464, 2025). "By performing histological and molecular analyses, we demonstrated that the ovarian neoplasms were sex cord-stromal tumors which expressed granulosa cell markers including FOXL2, INHA, and FOXO1." (PMID 29221447, 2017). "To define the molecular characteristics of ovarian tumors in TGFBR1-CAG9Cre mice, we performed immunostaining to examine the expression of a granulosa cell lineage marker FOXL2 and three other granulosa cell-expressed proteins, FOXO1, INHA, and AMH." (PMID 29221447, 2017). "The localization of FOXL2, INHA, FOXO1, AMH, and DDX4 was detected in the granulosa cell or oocyte compartment of control ovaries, while ovarian tumor tissues from TGFBR1-CAG9Cre mice were immunoreactive with FOXL2, INHA, and FOXO1, supporting the development of GCTs in these mice." (PMID 29221447, 2017).
pancreatic adenocarcinoma (4 papers, 2019 to 2023). "Exemplifying TFs from forkhead box family, FOXO1 regulates LINC01197 to assist its tumor-suppressive functions in pancreatic adenocarcinoma." (PMID 38111678, 2023). "GIMAP7 was associated with the infiltration levels of immunocytes, and the inhibition of GIMAP7 would down-regulated the level of FOXO1 expression in pancreatic adenocarcinoma." (PMID 33115964, 2020). "The FOXO1-regulated lncRNA LINC01197 inhibits pancreatic adenocarcinoma cell proliferation." (PMID 33230459, 2020).
prostate adenocarcinoma (4 papers, 2019 to 2024). "Paradoxically, FOXO1 has also been found to be activated by CDK1 to induce apoptosis gene activation in post-mitotic neurons but FOXO1 phosphorylation by CDK1 promotes its inhibition in human prostate adenocarcinoma cells." (PMID 32372224, 2020). "miR-708 targeted Sestrin-3 to inhibit Forkhead Box O1 (FOXO1) phosphorylation, resulting in apoptosis of prostate adenocarcinoma cells and AKT-inactivated NEPC cells, the latter of which was consistent with the progression of tumor xenografts in mice under miR-708 treatment." (PMID 31583122, 2019).
urothelial bladder cancer (4 papers, 2019 to 2024). "It has been demonstrated that the ENT treatment increased the expression of FOXO1 in urothelial bladder cancer cells." (PMID 36430344, 2022). "Taken together, the protein expression results demonstrate that DAC and ENT treatment increase FoxO1 expression in urothelial bladder cancer cells." (PMID 32028599, 2020). "Furthermore, our findings highlight the pivotal role of TSC in downregulating Axl expression and activating FoxO1, influencing the fate of urothelial bladder cancer cells." (PMID 38675387, 2024). "Conversely, in non-metastatic bladder transitional cell carcinoma T24 cells, miR-145 overexpression inhibited cell growth, which correlates with upregulation of FoxO1." (PMID 31013615, 2019).
vascular dementia (4 papers, 2021 to 2026). A degenerative vascular disorder affecting the brain. "There have been several findings that confirm that hydrogen sulfide attenuates apoptosis and neuronal injury in the hippocampus and that molecular hydrogen attenuates autophagic cell death via the FoxO1 pathway in mice with vascular dementia." (PMID 34746315, 2021). "It protects against vascular dementia by reducing MDA levels, inhibiting ROS production, increasing glutathione peroxidase and total thiol levels, and up-regulating Nrf2, FOXO1, FOXO3, and FOXO4, thereby reducing oxidative stress and improving learning and memory functions." (PMID 39169952, 2024).
acute lymphoblastic leukemia (3 papers, 2018 to 2025). Leukemia with an acute onset, characterized by the presence of lymphoblasts in the bone marrow and the peripheral blood. "The first B cell‐related study of FoxO1 inhibition was performed in B cell precursor acute lymphoblastic leukemia (BCP‐ALL), where the fine‐tuned FoxO1 activity allows for low‐level DNA damage susceptibility and clonal ALL cell evolution." (PMID 39533662, 2025). "The last evidence of FoxO1's oncogenic potential comes from the field of B cell precursor acute lymphoblastic leukemia (BCP‐ALL), the most common malignancy in children." (PMID 39533662, 2025). "FOXO1 inhibitors, particularly AS1842856, have been previously used in studies of B cell precursor acute lymphoblastic leukemia (BCP-ALL) and BL." (PMID 36282572, 2022).
amyotrophic lateral sclerosis (3 papers, 2016 to 2024). Amyotrophic lateral sclerosis (ALS) is a neurodegenerative disease characterized by progressive muscular paralysis reflecting degeneration of motor neurons in the primary motor cortex, corticospinal tracts, brainstem and spinal cord. "Thus, oxidative stress has been shown to regulate motor neuron death through the phosphorylation of FOXO1 by MST1 in amyotrophic lateral sclerosis (ALS) animal models." (PMID 27322327, 2016).
Arrhythmia (3 papers, 2012 to 2020). Any cardiac rhythm other than the normal sinus rhythm. "Indeed, in mice with cardiac‐specific deficiency of FOXO1, the heart demonstrated lowered systole, potentially arrhythmias, when compared to wild‐type mice." (PMID 32450616, 2020). "3-phosphoinositide-dependent protein kinase-1 (PDK1) is involved in the pathogenesis of arrhythmia, and its downstream factor, Forkhead box O1 (Foxo1), negatively regulates the expression of the cardiac sodium channel, Nav1.5." (PMID 25781322, 2015).
bladder tumors (3 papers, 2011 to 2025). "Immunohistochemistry showed significant correlations between p-FOXO1 expression and AR positivity in bladder tumors or ERβ positivity in UUT tumors, as well as between FOXO1 expression and ERα positivity or ERβ negativity." (PMID 32759680, 2020). "In addition, injection of FOXO1 inhibitor significantly accelerated the development of BBN-induced bladder tumors in female mice." (PMID 40486871, 2025).
carotid atherosclerosis (3 papers, 2014 to 2024). A thickening and loss of elasticity of the walls of carotid arteries that occur with formation of atherosclerotic plaques. "This study demonstrated associations of genetic variations at the SIRT1 and FOXO1 loci with carotid atherosclerosis and highlighted the need for further investigation by functional studies." (PMID 25273948, 2014). "Our study is the first to report a significant association of genetic polymorphisms at SIRT1 and FOXO1 with a carotid atherosclerosis." (PMID 25273948, 2014). "The rs10507486 and rs2297627 FOXO1 SNPs were shown to be associated with carotid atherosclerosis." (PMID 31492105, 2019). "The pathophysiological functions of SIRT1 and FOXO1 in vascular homeostasis and carotid atherosclerosis have been described within the last years and exert protective roles in case of SIRT1 and controversial roles for FOXO1." (PMID 25273948, 2014). "Association of genetic polymorphisms at the SIRT1 and FOXO1 loci with carotid atherosclerosis have not been reported before." (PMID 25273948, 2014). "It is not known, if genetic polymorphisms (SNPs) at the SIRT1 and FOXO1 have an influence on carotid atherosclerosis." (PMID 25273948, 2014). "Therefore, further replication studies and also functional studies are warranted to elucidate the molecular mechanism of this association and the role of these genetic variations at SIRT1 and FOXO1 in carotid atherosclerosis." (PMID 25273948, 2014). "However, the functional consequences of SIRT1 and FOXO1 genetics in regulation of carotid atherosclerosis remain incompletely understood and should be investigated in further functional studies." (PMID 25273948, 2014).
cerebral aneurysms (3 papers, 2022 to 2024). "Furthermore, recent studies have shown that miR-124-5p can delay the progression of cerebral aneurysms by regulating FoxO1, which shows that the regulation of FoxO1 by miR-124-5p is critical in the disease progression." (PMID 38549714, 2024).
chronic obstructive pulmonary disease (3 papers, 2016 to 2025). A chronic and progressive lung disorder characterized by the loss of elasticity of the bronchial tree and the air sacs, destruction of the air sacs wall, thickening of the bronchial wall, and mucous accumulation in the bronchial tree. "In humans, moderate physical activity time positively correlated with SIRT1 and FOXO1 mRNA expression in PBMCs in chronic obstructive pulmonary disease (COPD) patients." (PMID 39264516, 2024).
gastric tumor (3 papers, 2011 to 2022). "In addition, miR-135b delivered to gastric tumors by EVs negatively regulates forkhead box O1 (FOXO1), a transcription factor associated with angiogenesis regulation, and this regulation results in enhancement of the proliferation, migration, and ring formation of vascular cells." (PMID 35972944, 2022). "To obtain a better understanding of the mechanism involved in the JNK-induced gastric tumor cell proliferation, we investigated the relationship between JNK and FOXO1." (PMID 27268017, 2016). "Thus, restoration of FOXO1 activity may be a useful tool to suppress gastric tumor promotion." (PMID 27268017, 2016).
gestational diabetes (3 papers, 2022 to 2023). Carbohydrate intolerance first diagnosed during pregnancy. "Although the role of miR-106a-5p in gestational diabetes has never been investigated, there is evidence of its implication in glucose homeostasis as it targets FOXO1, a key regulator of insulin signaling." (PMID 37298229, 2023).
glaucoma (3 papers, 2010 to 2021). Increased pressure in the eyeball due to obstruction of the outflow of aqueous humor. "The next strongest association was for rs2755237 close to FOXO1 (P = 3.70 × 10−3); in this instance with the CCT-decreasing allele C being associated with an increased risk of glaucoma (rs2755237-C allele glaucoma OR = 1.15)." (PMID 29760442, 2018). "The gene FOXO1 belongs to the forkhead family of transcription factors, the same family as the candidate gene FOXC1 (6q25) that was previously associated with early onset glaucoma (see Introduction)." (PMID 20485516, 2010).
HIV-1 infection (3 papers, 2014 to 2022). The type species of lentivirus and the etiologic agent of acquired immunodeficiency syndrome (AIDS). "We therefore hypothesized that the susceptibility to HIV-1 infection of FOXO1-inhibited resting T cells could be due to an increased cell metabolism." (PMID 31042779, 2019). "FOXO1 inhibition promotes HIV-1 infection in resting T-cells." (PMID 36685589, 2022). "FOXO1 inhibition makes resting CD4+ T cells permissive to HIV-1 infection." (PMID 31042779, 2019). "FOXO1 inhibition by AS1842856 makes resting T cells permissive to HIV-1 infection." (PMID 31042779, 2019). "In this context, it is interesting to note that FOXO1 is inhibited upon HIV-1 infection." (PMID 31042779, 2019). "Whatever it may be, the control by FOXO1 of the NFAT pathway could be another mechanism implemented by T cells to protect them from HIV-1 infection." (PMID 31042779, 2019). "Data showing an increase of viral replication kinetics after inhibition of FOXO1 in quiescent T cells treated with IL-7 now suggest that this molecule may be another molecular switch controlling HIV-1 infection and participating in the effects of this cytokine on the biology of HIV-1 in T cells." (PMID 31042779, 2019). "Taken together, these results demonstrate that FOXO1 is a major player in T lymphocyte/HIV-1 interaction and that its pharmacological inhibition is a new potential clinical strategy to eradicate latent provirus reservoirs during HIV-1 infection." (PMID 31042779, 2019). "Thus FOXO1 appears as an important player of the HIV-1/T-cell relationship and a new potential therapeutic target for intervention during HIV-1 infection." (PMID 31042779, 2019). "In this study we examine the consequences of HIV-1 infection to naïve and memory resting CD4+ T cells, finding that CD62L was specifically down-modulated, the early activation marker CD69 was upregulated, and that these occurred concomitantly with HIV-1 suppression of Foxo1 activity." (PMID 25330112, 2014).
Hypercholesterolemia (3 papers, 2019 to 2024). An increased concentration of cholesterol in the blood. "In this study, we found that high cholesterol induced apoptosis and autophagy via the ROS-mediated FOXO1 pathway in TDSCs, suggesting a new mechanism underlying hypercholesterolemia-induced tendinopathy." (PMID 32197645, 2020). "The present study indicated that high cholesterol induced apoptosis and autophagy through ROS-activated AKT/FOXO1 signaling in TDSCs, providing new insights into the mechanism of hypercholesterolemia-induced tendinopathy." (PMID 32197645, 2020). "First, we did not use apoptosis inhibitors, autophagy inhibitors, antioxidants, or FOXO1 signaling inhibitors in vivo to further detect whether apoptosis, autophagy, ROS, or FOXO1 signaling might be involved in the pathogenesis of tendinopathy in hypercholesterolemia." (PMID 32197645, 2020).
intracerebral hemorrhage (3 papers, 2022 to 2025). A cerebrovascular disorder characterized by bleeding into one or both cerebral hemispheres including the basal ganglia and the cerebral cortex. "Neuroinflammatory cell infiltration and microglia activation are inhibited through the PI3K/Akt/FOXO1 pathway, thus alleviating apoptosis and neurologic impairment after intracerebral hemorrhage." (PMID 35154571, 2022).